PDE10A (phosphodiesterase 10A)
Description:
Plays a role in signal transduction by regulating the intracellular concentration of cyclic nucleotides. Can hydrolyze both cAMP and cGMP, but has higher affinity for cAMP and is more efficient with cAMP as substrate. May play a critical role in regulating cAMP and cGMP levels in the striatum, a region of the brain that contributes to the control of movement and cognition.
Synonyms: ADSD2; HSPDE10A; IOLOD; PDE10A19; C6orf176; LNC473; bA142J11.1; LINC00473
Tractability: Small molecule: an approved drug acts on it; a structure with a bound ligand is known; a high-quality ligand is known; it has a high-quality binding pocket; it belongs to a druggable protein family. PROTAC: ubiquitination databases record sites on it; its protein half-life has been measured; a small molecule that binds it is known.
Target class: Phosphodiesterase 10A; Enzyme; Phosphodiesterase; Phosphodiesterase 10
Chemical probes: JNJ-42396302 (high quality), THPP-1 (high quality)
Gene: Protein-coding gene on chromosome 6 (165,327,287 to 165,988,117, reverse strand). Ensembl gene ENSG00000112541.
Subcellular location: Cytoplasm, cytosol
Pathways (Reactome):
Hemostasis: cGMP effects
Signal Transduction: G alpha (s) signalling events
Gene Ontology:
Molecular function: 3',5'-cGMP-stimulated cyclic-nucleotide phosphodiesterase activity; 3',5'-cyclic-AMP phosphodiesterase activity; 3',5'-cyclic-GMP phosphodiesterase activity; 3',5'-cyclic-nucleotide phosphodiesterase activity; cAMP binding; cGMP binding; cyclic-nucleotide phosphodiesterase activity; phosphoric diester hydrolase activity
Biological process: negative regulation of cAMP/PKA signal transduction; negative regulation of receptor guanylyl cyclase signaling pathway; cAMP catabolic process; cGMP catabolic process; signal transduction
Cellular component: cytosol; glutamatergic synapse; synapse
Genetic constraint (gnomAD): Loss-of-function variants: 12 observed, 45.49 expected, observed/expected ratio (o/e) 0.26, 90% interval 0.17 to 0.43. The upper end of that interval is the gene's LOEUF score, 0.43, which puts it in group 1 of 6, group 1 being the genes least tolerant of losing a copy. Missense variants: 332 observed, 603.73 expected, observed/expected ratio (o/e) 0.55, 90% interval 0.5 to 0.6. Synonymous variants: 206 observed, 222.39 expected, observed/expected ratio (o/e) 0.93, 90% interval 0.83 to 1.04.
Homologues: Orthologues: macaque PDE10A (98% identical), pig PDE10A (94% identical), dog PDE10A (93% identical), rat Pde10a (89% identical), chimpanzee PDE10A (76% identical), rabbit PDE10A (72% identical), mouse Pde10a (71% identical), guinea pig PDE10A (67% identical), tropical clawed frog pde10a (62% identical), zebrafish pde10a (62% identical), Caenorhabditis elegans pde-5 (28% identical). Paralogues in human: PDE2A (23% identical), PDE5A (23% identical), PDE11A (22% identical), PDE6A (18% identical), PDE6B (18% identical), PDE6C (18% identical), PDE4C (12% identical), PDE4A (12% identical), PDE4D (12% identical), PDE4B (11% identical), PDE9A (11% identical), PDE3B (11% identical), and 8 more.
Diseases named in the same sentence as PDE10A in open-access papers:
PDE10A is named in the same sentence as 135 diseases in open-access papers, as found by Europe PMC text mining. Sharing a sentence is not in itself a finding about the gene and the disease. The quoted sentences say what the papers report.
schizophrenia (46 papers, 2012 to 2026). A major psychotic disorder characterized by abnormalities in the perception or expression of reality. "Of the 11 known PDE families, PDE10A is of particular interest as it is mainly localized in the striatum, a brain region implicated in the pathogenesis of schizophrenia." (PMID 39857669, 2025). "Given its regulatory role in critical signaling pathways, PDE10A is implicated in the pathophysiology of multiple neuropsychiatric and neurodegenerative disorders, including schizophrenia, HD, PD, and Alzheimer’s disease (AD)." (PMID 41179677, 2025). "In schizophrenia, PDE10A is implicated due to its high expression in dopaminoceptive MSNs and its role in modulating both dopaminergic and glutamatergic signaling." (PMID 41179677, 2025). "High PDE10A expression in certain neurons such as in the striatum of the human brain causes various psychiatric/neurodegenerative disorders, including schizophrenia and Huntington’s disease." (PMID 34530505, 2022). "This outcome indicates an important role of PDE10A in striato-cortical interactions and that striatal dysfunction and cortical thinning are part of the same underlying pathophysiology in schizophrenia." (PMID 33917199, 2021). "The substantia nigra is a key nucleus in relation to the basal ganglia and thus, regional dysfunction of PDE10A is suggested to be associated with the pathophysiology of neuropsychiatric disorders like schizophrenia." (PMID 33917199, 2021). "The enzyme phosphodiesterase 10A (PDE10A) is abundant in striatal medium spiny neurons and has been implicated in the pathophysiology of schizophrenia in animal models and is investigated as a possible new pharmacological treatment target." (PMID 28267149, 2017). "Understanding whether and how this relates to changes in brain function in the striatum and its associated symptoms would help to clarify the role of PDE10A in schizophrenia." (PMID 31119377, 2020). "PDE10A has been mostly studied in the brain as it is associated with diseases such as the neurodegenerative genetic Huntington’s disease, psychosis, and schizophrenia." (PMID 27548062, 2016). "Currently, several PDE10A inhibitors are being examined as therapeutics in patients with schizophrenia." (PMID 40943492, 2025). "PDE10A inhibitors have been most extensively investigated for their efficacy in patients with schizophrenia." (PMID 39056811, 2024). "There is an ongoing study of the PDE10A inhibitor MK-8189 in 500 patients with acute schizophrenia, estimated to finish in July 2024 (NCT04624243)." (PMID 39056811, 2024). "Other potentially treatable conditions with PDE10A inhibitors include schizophrenia, Huntington’s disease, L-dopa-induced dyskinesia in Parkinson’s disease, and childhood-onset fluency disorder." (PMID 39056811, 2024). "Herein, we have shown that a dual inhibitor of PDE1B and PDE10A, compound 2, prevented and reversed schizophrenia-like behavioural alterations induced by ketamine, suggesting the potential of compound 2 as a promising therapy for schizophrenia." (PMID 36454774, 2022). "Pyrazoloquinoline 74 has been described as a potent, selective, and orally active phosphodiesterase 10A inhibitor (PDE10A) for the potential treatment of schizophrenia." (PMID 35408636, 2022). "While; the inhibition of PDE10A activity has generated much excitement as a potentially novel mechanism to treat the positive symptoms of schizophrenia." (PMID 36454774, 2022). "Mardepodect is a CNS penetrant PDE10A inhibitor, developed by Pfizer initially for schizophrenia and later repositioned for Huntington’s Chorea within the AMARYLLIS clinical trial." (PMID 34359681, 2021). "In conclusion, this follow-up study provided evidence for a relation between decreased PDE10A levels in the striatum and basal ganglia function, both at the neural and behavioral level, in schizophrenia." (PMID 33917199, 2021).
schizophrenia (continued). "Both PDE2A and PDE10A inhibitors are being studied in the clinic as potential treatments for schizophrenia, Huntington’s disease, Parkinson’s disease, and other movement and neuropsychiatric disorders." (PMID 34335180, 2021). "Although additional PDE10A inhibitors have advanced to early clinical safety studies, searches of company websites suggest that efforts regarding the PDE10A mechanism with respect to schizophrenia have been discontinued." (PMID 33551724, 2020). "Phosphodiesterase 10A inhibitor TAK-063 has shown effects that suggest efficacy in schizophrenia treatment." (PMID 31773211, 2020). "This study shows a negative relationship between striatal PDE10A and basal ganglia functioning, both at the neural and behavioral level, in patients with schizophrenia who show reduced PDE10A levels." (PMID 31119377, 2020). "Since publication, these tracers have been used for the study of PDE10A in HD, PD, and schizophrenia." (PMID 31541283, 2020). "If the inhibition of PDE10A is indeed a viable treatment option, an increase in striatal PDE10A levels in schizophrenia would be expected." (PMID 31119377, 2020). "Pharmacological inhibition of phosphodiesterase 10A (PDE10A) is being investigated as a treatment option in schizophrenia." (PMID 31119377, 2020). "With this in mind, we review the data on PDE10A inhibition as a step toward such back-translation, hopefully to inform new efforts to develop better therapeutics to treat psychosis and schizophrenia." (PMID 33551724, 2020). "Phosphodiesterase 10A (PDE10A) is mainly expressed in the brain, especially in neuronal cells of the striatum, with many different splice variants, and is associated with schizophrenia and neurodegenerative diseases." (PMID 32587621, 2020). "Here, this finding of reduced PDE10A in schizophrenia was followed up in the same sample to investigate the effect of reduced striatal PDE10A on the neural and behavioral function of striatal and downstream basal ganglia regions." (PMID 31119377, 2020). "This study aimed to explore the relationship between striatal PDE10A levels and neural and behavioral function of striatal and downstream basal ganglia regions, in patients with schizophrenia." (PMID 31119377, 2020). "As a consequence, inhibitors of PDE10A offer a promising therapeutic approach for the treatment or prevention of psychiatric disorders, especially schizophrenia and related diseases." (PMID 31216762, 2019). "The phosphodiesterase 10A (PDE10A) enzyme is involved in cellular signaling pathways in schizophrenia." (PMID 31216762, 2019). "PDE10A inhibitors are chosen with respect to the search for new antipsychotics in the field of schizophrenia research due to the high and exclusive expression of PDE10A in the striatum." (PMID 29098341, 2018). "In conclusion, for the first time, we have observed a lower striatal PDE10A expression in patients with schizophrenia." (PMID 28267149, 2017). "TAK-063 is a potent and selective phosphodiesterase 10A (PDE10A) inhibitor in clinical development for the treatment of schizophrenia." (PMID 27572830, 2016). "Accordingly, PDE10A inhibition can be a novel therapeutic approach for the treatment of schizophrenia with lower risks of these side effects." (PMID 25815469, 2015). "For instance, the PDE10A inhibitor, papaverine, was found to suppress conditioned avoidance responses in rats, suggesting potential therapeutic roles in schizophrenia and in Alzhemier’s disease." (PMID 25252626, 2014). "By addressing the limitations of current candidates and emphasizing the need for dual inhibitors, this review aims to guide future research efforts toward the discovery of more selective, potent, and clinically viable PDE1B and PDE10A inhibitors for schizophrenia." (PMID 41835457, 2026). "Together, these mechanisms suggest that targeting PDE1B and PDE10A could offer an innovative avenue for the comprehensive management of schizophrenia." (PMID 41835457, 2026).
schizophrenia (continued). "The decreased striatal PDE10A concentration in schizophrenia patients may correlate with increased MSN excitability." (PMID 38406202, 2024). "PDE10A inhibitors are of interest as potential therapeutics for several basal ganglia function disorders but have also been tested in disorders with more diffuse pathophysiologies, such as schizophrenia and Huntington’s disease." (PMID 39056811, 2024). "While the results to date of PDE10A inhibitors in schizophrenia have been mixed, these studies provide knowledge that may advance our understanding of the neurobiological basis of psychosis." (PMID 39056811, 2024). "Interestingly, PDE10A is an already knownsafe druggable target, since several PDE10A inhibitors have already passed phaseI clinical trials in humans for the treatment of schizophrenia andHuntington’s disease." (PMID 39076707, 2023). "In addition, one study looking at patients with schizophrenia found reduced Pde10a and medial prefrontal cortex thinning, another aspect observed in the SncaNLS mice." (PMID 35179202, 2022). "PDE10A has been of recent interest in schizophrenia research." (PMID 35701411, 2022). "Several reports have suggested that PDE10A inhibitors may present a promising approach for the treatment of positive symptoms of schizophrenia, whereas PDE1B inhibitors may present a novel mechanism to modulate cognitive deficits." (PMID 36454774, 2022). "Accordingly and comparable to PDE2A, PDE10A activity is related to neurodegenerative and neuropsychiatric diseases like Huntington’s disease, Parkinson’s disease, Alzheimer’s disease, dementia, schizophrenia and depression." (PMID 33917199, 2021). "The aim of this study was to investigate whether an earlier reported reduction in striatal PDE10A levels relates to striatal function in schizophrenia." (PMID 31119377, 2020). "Indeed, PDE10A inhibitors have shown promising results across a range of symptoms in preclinical schizophrenia models." (PMID 31119377, 2020). "Accordingly, the ability of PDE10A inhibitors to effectively block hyperactivity induced by NMDA receptor channel blockers in rodents was significantly supportive for advancing this class into clinical trials as a therapeutic for schizophrenia." (PMID 33551724, 2020). "Furthermore, inhibition of PDE10A was shown to have a positive regulatory effect on basal ganglia function, making it a potential target for the treatment of psychosis and schizophrenia." (PMID 32938236, 2020). "PDE10A acts postsynaptically on striatal dopamine signaling by regulating neuronal excitability through its inhibition of cyclic adenosine monophosphate (cAMP), and we recently found it to be reduced in schizophrenia compared to controls." (PMID 31119377, 2020). "Accumulating preclinical evidence indicates that PDE inhibitors promote learning and memory, and inhibition of PDE10A has been suggested as a promising therapeutic strategy for psychiatric and neurodegenerative diseases, based on its efficacy in animal models of schizophrenia and AD." (PMID 33273904, 2020). "Several PDE10A inhibitors were tested in various settings in patients with schizophrenia." (PMID 33551724, 2020). "However, we recently found that striatal PDE10A was reduced in patients with schizophrenia compared to controls." (PMID 31119377, 2020). "With this in mind, we review the data on PDE10A inhibition as a step toward back-translating the limited antipsychotic efficacy of PDE10A inhibitors, hopefully to inform new efforts to develop better therapeutics to treat psychosis and schizophrenia." (PMID 33551724, 2020). "The findings are in line with a role for PDE10A in striatal functioning, and suggest that reduced striatal PDE10A may contribute to cognitive symptoms in schizophrenia." (PMID 31119377, 2020). "In conclusion, PDE10A may be important for functioning in the striato-cortical interaction and in the pathophysiology of schizophrenia." (PMID 28267149, 2017).
schizophrenia (continued). "A reduction of prefrontal cortical thickness is common in schizophrenia, but how this relates to PDE10A expression is unknown." (PMID 28267149, 2017). "Inhibition of phosphodiesterase (i.e. PDE10A) and activation of metabotropic glutamate receptor (mGluR2) signaling are believed to provide antipsychotic efficacy in schizophrenia, but it is unclear whether this occurs with cognition-enhancing potential." (PMID 26808689, 2016). "Due to the high PDE10A density in striatum, this enzyme is suggested to play an important role in the pathophysiology of neurodegenerative and neuropsychiatric disorders such as Huntington’s disease, Parkinson’s disease, and schizophrenia." (PMID 27213312, 2016). "PDE10A inhibitors also could mimic D2 antagonist effects by preferentially activating indirect pathway MSNs, offering potential therapeutic benefits for psychosis, schizophrenia, Tourette syndrome, and other movement disorders." (PMID 41179677, 2025). "PDE10A inhibitors are a novel class of drug that continues to be explored for a wide range of indications (schizophrenia, Tourette syndrome, childhood-onset fluency disorder, L-dopa-induced dyskinesia in Parkinson’s disease) and may have potential applicability in others." (PMID 39056811, 2024). "Mardepodect, a Phase 3 clinical candidate developed by Pfizer as PF-02545920 for schizophrenia and more recently repositioned for Huntington’s Disease, is a potent PDE10A inhibitor with CNS penetrant properties that may make it suitable for repositioning in GBM." (PMID 34359681, 2021). "However, perhaps the most significant gap in our knowledge regarding PDE10A inhibitors as well as D2 receptor antagonists is a clearer understanding of the effects of such compounds in humans, both in healthy individuals and those suffering from schizophrenia." (PMID 33551724, 2020). "Thus, it might be too early to dismiss PDE10A as a key factor in schizophrenia pathophysiology or PDE10A inhibition as a potential new treatment." (PMID 28267149, 2017). "For example, clinical PET studies clearly showed a pathological loss of striatal PDE10A in Huntington’s disease but indicated that the expression of PDE10A is not altered in schizophrenia leading to a discussion on the involvement of the PDE10A protein in schizophrenia." (PMID 27213312, 2016). "Taken together, the preclinical data validate PDE10A as a potential target for therapeutic intervention, and support further investigation of the safety, tolerability, and potential multidimensional efficacy of selective PDE10A inhibitors in people with schizophrenia." (PMID 27572830, 2016). "For that purpose, quantification of striatal PDE10A levels by PET using [11C]32 was performed in 16 healthy controls and 10 schizophrenia patients treated with diazepines." (PMID 33917199, 2021). "In summary, there is ample evidence for aberrant striatal functioning in schizophrenia, but while increased activity in the striatum in rodents following PDE10A inhibition has been observed, the relationship between striatal function and PDE10A in schizophrenia is still unknown." (PMID 31119377, 2020). "The primary aim of our study was to evaluate the expression of PDE10A with the newly validated and sensitive ligand [11C]Lu AE92686 in patients with schizophrenia treated with diazepines compared to healthy controls." (PMID 28267149, 2017). "Phosphodiesterase 10A (PDE10A) inhibition is a novel and promising approach for the treatment of central nervous system disorders such as schizophrenia and Huntington’s disease." (PMID 25815469, 2015). "Several PDE10A inhibitors have entered Phase I and II clinical trials for non-oncologic indications, such as schizophrenia (ClinicalTrials.gov Identifiers: NCT00570063, NCT02477020, NCT02019329, NCT01568203), and have shown favorable safety profiles." (PMID 41179677, 2025).